IL1B (interleukin 1 beta)
Diseases named in the same sentence as IL1B in open-access papers (continued):
Sharing a sentence is not in itself a finding about the gene and the disease.
Arthritis (continued). "The anti-arthritis mechanism of action for ASHW was established through the suppression of pro-inflammatory cytokines such as IL-1β, IL-6, TNF-α; and upstream regulator, NF-κB." (PMID 31142786, 2019). "Consistent with the role of mutated NLRC4 in the development of joint pathologies, transgenic mice expressing constitutively active NLRC4 produce high levels of IL-1β and IL-18, and develop arthritis." (PMID 31520179, 2019). "The expression of cell cycle regulators p16 and p21 were changed upon treatment with romidepsin via suppression of IL-1β in an animal model of arthritis." (PMID 30841513, 2019). "The arthritis-related genes IL1β, IL6 and TNFα were only found up-expressed in Ficat IV stage which indicated that the arthritis-related molecular changes were not significant in the progression of ONFH before Ficat III stage." (PMID 30671313, 2019). "Concerning the effects of IL-38 on arthritis, the induction of serum-transfer induced arthritis (STIA) in IL-38-deficient mice determines a more severe phenotype and a higher joint expression of IL-1β and IL-6 compared with littermates control." (PMID 30871134, 2019). "Although dual blockade of TNF-α and IL-1β, or IL-1β and IL-17A reduces murine arthritis, spontaneous skin infections were observed." (PMID 30626891, 2019). "The strategy uses IL-1β to stimulate FLS in anti-arthritis drug discovery, which was used as well in this study." (PMID 31835494, 2019). "Overall, these finding underscore the potential relevance of CTHRC1 as a marker in arthritis pathogenesis and also support our earlier findings showing positive association of CTHRC1 with IL-1β and IL-6 in a mouse model of arthritis." (PMID 31249576, 2019). "In a collagen-induced experimental arthritis model, JQ1 induced attenuation in the arthritis severity score associated to lower serum levels of proinflammatory cytokines, including IL-1β, IL-6, IL-17, and IL-18." (PMID 31780938, 2019). "For example, mice with ALOX15, an isoform of ALOX8, knocked out had arthritis, with increased levels of IL-6 and IL-1β as compared with their wild-type controls, and the level of KC was correlated to their body weight loss." (PMID 31013822, 2019). "The anti-inflammatory effects of JC3 were investigated in vitro using interleukin-1beta (IL-1β)-stimulated fibroblast-like synoviocytes (FLS) derived from arthritis patients." (PMID 30565030, 2019). "Combinations of IL-1β and other proinflammatory cytokines reportedly promote the severity of arthritis." (PMID 31614911, 2019). "Hyper-activation of the pyrin inflammasome by MEFV-activating mutations causes Familial Mediterranean fever (FMF), a disease that is characterized by high levels of IL-1β, IL-6, IL-8, and IL-12, recurring fever episodes, arthritis, and low bone mass." (PMID 31520179, 2019). "One of the most potent inflammatory factors involved in hyaline cartilage degradation in many forms of arthritis is interleukin (IL)-1β." (PMID 31067826, 2019). "In this study, we simulated the OA model of chondrocytes in vitro by exposure to IL-1β, which is one of the most prominent mediators of cartilage degradation and joint inflammation." (PMID 31888697, 2019). "Although Col V oral administration is also effective for the reduction in IL-17 in our induced arthritis model, the IL-1β and TNF cytokines seem to be a therapeutic target of particular interest in the treatment of arthritis." (PMID 30059520, 2018). "In our study, despite the low amount of IL-1β, anti-inflammatory effects of probiotics during chronic phase of CFA-induced arthritis were occurred via a pathway different from the direct inhibition of serum IL-1β pathway." (PMID 30719247, 2018). "Whereas IL-1β is the main cytokine involved in the destruction of cartilage and bone, this finding is of great importance for a possible therapy for arthritis." (PMID 30059520, 2018).
Arthritis (continued). "In fact, budlein A ameliorates murine antigen-induced arthritis by inhibiting NF-κB activation and thereby Il-33, Tnf-α, Il-1β, endothelin-1, and Cox-2 mRNA expression in the knee joint." (PMID 30319413, 2018). "We also observed reductions in TNF-α, IL-17A, IL-1β expression and bone destruction even when transfer occurred after the onset of arthritis." (PMID 29535721, 2018). "Requirement for the APC derived cytokines, TNF-α and IL-1β for arthritis induction and perpetuation is obvious." (PMID 29495570, 2018). "In murine models of acute arthritis, IL-1β inhibition during onset of arthritis results in effective suppression of joint swelling and influx of inflammatory cells." (PMID 30075804, 2018). "Body weight, hind paw swelling, TNF-α and IL-1β levels, arthritis scores, and histopathological parameters were assessed." (PMID 30154719, 2018). "In IL-1β-induced arthritis mice, there were intense staining of TNF-α but weak staining of SATB2 in mature osteoblasts." (PMID 29435145, 2018). "osteoarthritis is the most common form of arthritis and involves multiple proinflammatory cytokines, including IL-1β, TNF, and IL-6." (PMID 30542285, 2018). "It has been reported that p38MAPK activation during arthritis can increase the production of proinflammatory cytokines, including IL-1β which can, in turn, strengthen the hyperalgesia as one of the inflammatory symptoms (Tekieh, Zaringhalam, & Akhtari, 2014)." (PMID 30719247, 2018). "This is likely to contribute to RA disease progression since the level of IL-1β in the joint increases with the onset of arthritis and correlates highly with arthritis scores." (PMID 30622982, 2018). "For instance, bispecific monoclonal antibodies recognising IL-17A and IL-1β have been recently tested by Li and colleagues and showed to be effective to ameliorate the outcome of animal models of arthritis while human studies are underway." (PMID 29425183, 2018). "IL-1β and TNFα are the main cytokine instigators of cartilage degeneration in arthritis, and these induce MMP in chondrocyte cells." (PMID 29463254, 2018). "Gout is a common inflammatory joint disorder, and specific inhibition of IL-1β is approved by the U.S. Food and Drug Administration and the European Medicines Evaluation Agency for reducing the number of gout attacks." (PMID 30075804, 2018). "In situ hybridization revealed a positive signal for Spag11c mRNA in chondrocytes of the hyaline cartilage and in cells from the synovial membrane of the knee joint from control and mice submitted to mBSA/IL-1β-induced arthritis." (PMID 28587618, 2017). "Although none of the histopathological parameters was significantly reduced in comparison to animals submitted to mBSA/IL-1β-induced arthritis, either pre-injected with vehicle or transduced with the control lentivirus pWPXLd-IG." (PMID 28587618, 2017). "Herein, both strategies of tryptase inhibition reduced oedema formation, but only in the late phase of mBSA/IL-1β-induced arthritis, thus indicating that mast cell accumulation and/or Mcpt-6 upregulation occur late in this model." (PMID 28587618, 2017). "FLT-1 expression in arthritis is stimulated by two the most important proinflammatory cytokines - IL-1β and TNF-α, which can mediate the progression of bone destruction." (PMID 28323906, 2017). "IL-1β levels didn’t correlate with the arthritis score (r = 0.14, p = 0.4) and quite surprisingly correlated negatively with the ankle diameter (r = -0.46, p = 0.015, not shown)." (PMID 28759646, 2017). "To investigate the effect of soya-cerebroside on IL-1β-induced joint inflammation, we intra-articularly injected recombinant human IL-1β (rhIL-1β) into the rat knee joint to induce synovial inflammation." (PMID 28225075, 2017). "As pro- or anti-inflammation cytokines are often related to the pathology of arthritis, we also examined the secretion levels of IL-1β, IL-6, IL-17A, TNF-α and IL-10 in AA models." (PMID 28352114, 2017).
Arthritis (continued). "Peptide treatment reduced joint IL-1β by an average of 44% (P = 0.0054), which coincided with the marked reduction in arthritis severity in RTD-1 treated animals after 4 days of treatment (P = 0.0044)." (PMID 29145473, 2017). "We show that the aberrant microbiota in IL1rn−/− mice have the capacity to enhance LP Th17 cells which are associated with arthritis, likely via TLR4-induced production of IL-1β, IL-6, and IL-23." (PMID 28645307, 2017). "TNF, IL‐6 and IL‐1β blocking agents in RA patients resulted in a decline in disease severity and relief of arthritis symptoms." (PMID 29226077, 2017). "GPR91-deficient mice, which lack a succinate receptor, show reduced macrophage activation and production of IL-1β in an animal model of arthritis." (PMID 28569176, 2017). "A key feature of arthritis is inflammation, where pro-inflammatory cytokines such as interleukin 1 beta (IL-1β) are important mediators." (PMID 28122611, 2017). "This lead to inhibition of gene expression of proinflammatory cytokines (TNF-α and IL-1β) in adjuvant-induced rat arthritis." (PMID 29166937, 2017). "A significant correlation was observed between IL-6, IL-17A as well as IL-1β hind paw gene expression levels and the corresponding hind paws arthritis score, and ankle diameter." (PMID 28759646, 2017). "We also identified ROS as the key regulator of IL-1β production in a serum-induced arthritis mouse model through an inflammasome-independent pathway." (PMID 29228045, 2017). "Of interest at this time of arthritis, plasma IL-1β and MCP-1 levels are elevated in AIA like at day 11, but additionally TNF-α and MIP-1α increased." (PMID 26761790, 2016). "During arthritis, IL-1β-induced catabolic processes promote matrix degradation and result in the formation of microcracks in the cartilage, which leads to FGF-2 release." (PMID 26811540, 2016). "In the present study, we utilized the chondrocytic ATDC5 cell line to examine the role of IL-1β, the major inflammatory cytokine during arthritis, in the expression of the pro-angiogenesis factor FGF-2." (PMID 26811540, 2016). "A trend for downmodulation of Il1b, the key cytokine driving K/BxN arthritis; Ly6g, a marker of neutrophil influx; and Ptsg2 (cyclooxygenase-2), essential for PG biosynthesis, was detected in mice given 17R-RvD1." (PMID 27158677, 2016). "Some studies have indicated or implied that piperine alleviates chronic inflammatory diseases (such as diabetic nephropathy and arthritis) by suppressing inflammasome activation and thus inhibiting IL-1β release." (PMID 27812336, 2016). "As IL-1β is a crucial mediator of the inflammatory response and plays an important role in arthritis, it is tempted to know if succinate contributed to IL-1β production in activated fibroblasts." (PMID 28003810, 2016). "Cartilage degradation in arthritis is recognized to be induced by inflammatory cytokines, such as interleukin (IL)-6, IL-1β, and tumor necrosis factor-α (TNF-α)." (PMID 27411719, 2016). "The result is consistent with the previous finding that Sin ameliorates arthritis via suppressing the production of pro-inflammatory cytokines IL1β and IL6 in collagen-induced arthritic rats." (PMID 27869674, 2016). "We also determined that 17R-RvD1 reduced systemic KC (CXCL1) levels, a principal chemokine that recruits neutrophils, and downregulated Il1b transcripts, a key cytokine that amplifies arthritis." (PMID 27158677, 2016). "IHC (immunohistochemistry) staining from a CIA (collagen-induced arthritis) mouse model also demonstrates that arthritis increased the expression of IL-1β and FGF-2, as well as EPC homing in articular cartilage." (PMID 26811540, 2016). "Targeting IL-1β and components of the receptor for IL-1β in various rodent models of arthritis is effective in reducing inflammation and particularly articular damage." (PMID 26839814, 2015).
Arthritis (continued). "In different animal models of arthritis, the antagonism of IL-1β significantly reduced cartilage damage, independently of a decrease of the inflammatory markers." (PMID 25954061, 2015). "The importance of IL-1β in onset arthritis is further highlighted by reports of its ability to promote the differentiation of Th17 cells." (PMID 26669668, 2015). "Proteinase 3, a neutrophil protease, cleaves pro-IL-1β near to the caspase-1 binding site to produce an active protein, and inhibiting this protease is protective in a mouse model of arthritis." (PMID 26324708, 2015). "A study using an antibody-induced arthritis model has shown that IL-1β is required for disease progression." (PMID 29124228, 2015). "In the light of its catabolic effects, IL-1β has been widely used to mimic arthritis in in vitro studies." (PMID 25856795, 2015). "Th17 cells are the main pathogenic cell type in many models of autoimmunity, including experimental autoimmune encephalomyelitis (EAE), acute inflammatory arthritis [methylated bovine serum albumin (mBSA)/IL-1β] arthritis) and collagen-induced arthritis (CIA)." (PMID 26081345, 2015). "In different experimental models of arthritis, it has been shown that an increased production of IL-1β is able to directly activate osteoclasts, thus inducing the bone erosions." (PMID 25954061, 2015). "Concomitant ablation of MyD88 reversed the effects of mast cell-specific A20 loss during arthritis induction to a large extent, indicating essential roles for IL-33, TLR ligands, and/or IL-1β." (PMID 24453940, 2014). "Although, the interplay of various cytokines is unclear in this context, interleukin 1β (IL-1β), a major proinflammatory cytokine known to be involved in the pathogenesis of arthritis, is the focus of our present case report." (PMID 24886556, 2014). "The elevated levels of inflammatory IL-1β aggravated the severity of arthritis attributable to meniscal tear in both patients, as found in follow-up visits." (PMID 24886556, 2014). "The experimental results show that both the CsA and the glycyrol treatments reduced the mean arthritis scores, and reduced the contents of IL-1β, TNF-α, IL-6, and IL-17 in the serum." (PMID 25036817, 2014). "Although the exact molecular mechanisms responsible for cartilage and bone destruction have not been elucidated, studies have shown that pro-inflammatory cytokines TNF-α, IL-1β, and IL-6 play a critical role in the pathological process of arthritis." (PMID 25276195, 2014). "IL-1RaKO mice that used in our experiments lack the IL-1β receptor antagonist, which blocks IL-1β, and develop spontaneous arthritis as they age." (PMID 24558360, 2014). "Rats with FCA-induced arthritis had significantly (P<0.01) increased IL-1β, IL-6 and TNF-α expression levels compared with those in the normal control group." (PMID 25289073, 2014). "Animals were assessed for arthritis symptoms using a clinical score, cytokine levels (human TNFα, IL-1β and IL-6) in sera and joints, and histopathology." (PMID 25344414, 2014). "Some studies showed that somatostatin stimulates the production of IL-1β, TNF-α, and/or IL-6 by human blood cells, as well as the expression of IL-1β in articular tissues of rats with ongoing adjuvant-induced arthritis." (PMID 25530957, 2014). "Nonetheless, we have previously reported increased levels of IL-1β in very recent onset arthritis and in the synovial fluid of established RA patients." (PMID 24623960, 2014). "Patient 1 is a 30-year-old man with KL grade 1 arthritis of the knee with relatively high IL-1β levels (2000.0±15.7pg/ml)." (PMID 24886556, 2014).
Arthritis (continued). "Because the pattern of effects of IL-1β on sensory neurons of the joint (opposite effects on C- and Aδ-fibers) is different to that of TNF-α and IL-6, it is an intriguing question how neutralization of IL-1β affects pain in arthritis." (PMID 25606597, 2014). "HLXL-treated rats with AA showed decreased arthritis scores as well as the levels of proinflammatory cytokines (IL-1β, IL-6, IL-17, TNF-α), chemokines (RANTES, MCP-1, MIP-1α, GRO/KC), and MMPs." (PMID 23476694, 2013). "For comparison, and in agreement with previously published data, IL-1RI, IL-1β and IL-1Ra mRNAs were present in inflamed joints of mice with CIA with a significant correlation between IL-1β mRNA levels and the severity of arthritis." (PMID 23452551, 2013). "A pathogenic factor in the development of arthritis is inflammation driven by proinflammatory cytokines, especially TNF, IL-1β, IL-6, and IL-17." (PMID 24286140, 2013). "On the other hand when IL-1β activity is unopposed, like in IL-1RA knot-out mice (C57BL/6J), causes autoimmunity and arthritis that closely resembled RA in humans." (PMID 23874332, 2013). "Microarray analysis of biopsies of inflamed synovium during antigen induced arthritis (AIA) showed an increased M1 signature characterized by upregulation of IL-1β, IL-6 and FcγRI starting from day 1 and lasting up until day 7 after arthritis induction." (PMID 23468840, 2013). "IL-5 and IL-13 are cytokines related to arthritis suppression, while tissue-destructive cytokines IL-1β and IL-6 induce Th17 cells and promote osteoclastogenesis." (PMID 24456966, 2013). "It was reported that the expression of IL-1β increased and arthritis was ameliorated with anti-IL-1β treatment in IFN-γ deficient C57BL/6 mice." (PMID 23613752, 2013). "IL-1β and TNF-α are associated with the development of early arthritis, whereas IL-1β maintains the inflammatory reaction in later stages." (PMID 23597113, 2013). "In a rat model of arthritis, artesunate treatment significantly attenuated inflammation and cartilage damage by decreasing the levels of IL-1β, IL-17 and TNF in rat’s hind paws." (PMID 24180288, 2013). "IL-1β and IL-1 receptor neutralizing antibodies are currently tested in arthritis and joint diseases." (PMID 23984335, 2013). "It has been suggested that TLR4-mediated signals promote joint inflammation by increasing levels of either IL-17 or IL-1β in murine arthritis models." (PMID 23036692, 2012). "We observed induction of IL-1β, IL-6 and IL-17, cytokines already described as key players in the arthritis process and clinically used as therapeutic targets." (PMID 22414623, 2012). "Neutralization of visfatin by its inhibitor (APO866) effectively reduced arthritis severity in mice with comparable activity to etanercept, and decreased pro-inflammatory cytokine (IL-1β and IL-6) secretion in affected joints." (PMID 22584415, 2012). "Correspondingly, histological measures of arthritis were reduced, as was tissue expression of IL-6, IL-1β and TNF-α." (PMID 23071771, 2012). "Taken together these data demonstrate an early increase in systemic inflammation in mice with arthritis treated with MSCs which is mediated predominantly through IFNγ, IL-1β and IL-17." (PMID 22812502, 2012). "Injection of recombinant IFN-γ, IL-12 or IL-1β into TLR4-/- mice restored arthritis as compared to WT mice, indicating that these pro-inflammatory cytokines contribute to the pathogenesis of TLR4-mediated joint inflammation in antibody-induced arthritis." (PMID 23036692, 2012). "Many studies are actually conducted to target IL-17 in arthritis models because of its potential synergistic effects with IL-1β, IL-6, and TNF-α in inducing cytokine expression and joint damage." (PMID 22414623, 2012). "IL-1β, IL-6, and TNFα are elevated in human RA synovium and have also been shown to contribute to the development of arthritis in animal models." (PMID 22414623, 2012).